INTS4 (integrator complex subunit 4)
Description:
Component of the integrator complex, a multiprotein complex that terminates RNA polymerase II (Pol II) transcription in the promoter-proximal region of genes. The integrator complex provides a quality checkpoint during transcription elongation by driving premature transcription termination of transcripts that are unfavorably configured for transcriptional elongation: the complex terminates transcription by (1) catalyzing dephosphorylation of the C-terminal domain (CTD) of Pol II subunit POLR2A/RPB1 and SUPT5H/SPT5, (2) degrading the exiting nascent RNA transcript via endonuclease activity and (3) promoting the release of Pol II from bound DNA. The integrator complex is also involved in terminating the synthesis of non-coding Pol II transcripts, such as enhancer RNAs (eRNAs), small nuclear RNAs (snRNAs), telomerase RNAs and long non-coding RNAs (lncRNAs). Within the integrator complex, INTS4 acts as an scaffold that links INTS9 and INTS11. Mediates recruitment of cytoplasmic dynein to the nuclear envelope, probably as component of the integrator complex.
Synonyms: Int4; MGC16733; MST093
Tractability: PROTAC: UniProt records ubiquitination sites on it; ubiquitination databases record sites on it; its protein half-life has been measured.
Gene: Protein-coding gene on chromosome 11 (77,874,418 to 77,994,850, reverse strand). Ensembl gene ENSG00000149262.
Subcellular location: Nucleus; Cytoplasm
Subcellular location (Human Protein Atlas): Nucleoli rim
Pathways (Reactome):
Gene expression (Transcription): RNA polymerase II transcribes snRNA genes
Gene Ontology:
Molecular function: protein binding; protein-macromolecule adaptor activity
Biological process: regulation of transcription elongation by RNA polymerase II; RNA polymerase II transcription initiation surveillance; snRNA processing
Cellular component: cytoplasm; INTAC complex; integrator complex; nucleolus; nucleus; nucleoplasm
Genetic constraint (gnomAD): Loss-of-function variants: 42 observed, 74.33 expected, observed/expected ratio (o/e) 0.57, 90% interval 0.44 to 0.73. The synonymous counts are far from expectation, so gnomAD's model fits this gene poorly and the ratio says little. Missense variants: 608 observed, 800.93 expected, observed/expected ratio (o/e) 0.76, 90% interval 0.71 to 0.81. Synonymous variants: 221 observed, 288.01 expected, observed/expected ratio (o/e) 0.77, 90% interval 0.69 to 0.86.
Homologues: Orthologues: chimpanzee INTS4 (100% identical), macaque INTS4 (99% identical), guinea pig INTS4 (98% identical), rabbit INTS4 (98% identical), mouse Ints4 (97% identical), rat Ints4 (96% identical), tropical clawed frog ints4 (84% identical), zebrafish ints4 (79% identical), Drosophila melanogaster IntS4 (36% identical), Caenorhabditis elegans ints-4 (25% identical).
Diseases named in the same sentence as INTS4 in open-access papers:
INTS4 is named in the same sentence as 5 diseases in open-access papers, as found by Europe PMC text mining. Sharing a sentence is not in itself a finding about the gene and the disease. The quoted sentences say what the papers report.
bladder cancer (1 paper, 2022). "Previously, researches demonstrated circRNA ACVR2A suppresses bladder cancer progression through regulating miR-626/EYA4 axis; CircRNA INTS4 promotes tumorigenesis in bladder cancer via miR-146b/CARMA3 axis." (PMID 33656636, 2022).
liver cancer (1 paper, 2024). An epithelial or non-epithelial malignant neoplasm that arises from the liver. "The expression of INTS1, INTS4, INTS7, and INTS8 increased with tumor progression, with all mentioned genes reflecting statistical differences in at least two groups of liver cancer tumor grades comparison." (PMID 38926181, 2024).
cancer (4 papers, 2017 to 2024). A tumor composed of atypical neoplastic, often pleomorphic cells that invade other tissues. "Conversely, INTS1 and INTS4 were mutated in almost all cancer types, at low rates." (PMID 28468258, 2017). "Furthermore, we observed that the co-expressed genes of INTS1, INTS4, INTS7, and INTS8 were involved in diverse processes associated with cancer development, underscoring their significant role in HCC progression." (PMID 38926181, 2024). "Among these APAs, 5 APAs (INTS4, SLC27A3, BCCIP, PLK3, HR) were differentially expressed in CRC tissues, when compared with para-cancer tissues." (PMID 35487956, 2022).
tumor (1 paper, 2024). "We then examined the expression of proteins associated with INTS1, INTS3, INTS4, INTS7, and INTS8 in HCC through the Clinical Proteomic Tumor Analysis Consortium (CPTAC) and Human Protein Atlas (HPA) databases." (PMID 38926181, 2024). "Our analysis indicated that INTS1, INTS4, INTS7, and INTS8 were highly expressed in HCC tissues, with their expressions closely correlated with tumor grade and poor prognosis of HCC patients." (PMID 38926181, 2024). "In this study, we discovered that INTS1, INTS4, INTS7, and INTS8 exhibited high expression levels in tumor tissues compared to normal tissues in both the UALCAN and GEPIA2 systems (P < 0.05)." (PMID 38926181, 2024). "Subsequently, we investigated whether the expression levels of INTS1, INTS4, INTS7, and INTS8 correlated with patient tumor staging." (PMID 38926181, 2024). "Therefore, we analyzed the differential expression of INTS1, INTS3, INTS4, INTS7, and INTS8 in normal, further tumor, and metastatic HCC tissues using the TNM plotter." (PMID 38926181, 2024).
INTS4 also shares sentences with these, for which no sentence is quoted: breast tumors (1 paper).